LIFR (LIF receptor subunit alpha)
Diseases named in the same sentence as LIFR in open-access papers (continued):
Sharing a sentence is not in itself a finding about the gene and the disease.
pancreatic cancer (continued). "Of note, pancreatic carcinoma cells constitutively express LIF and its heterodimer receptor (LIFR and gp130), and TNFα, IL1β or LIF itself enhanced the expression of LIF mRNA." (PMID 35565186, 2022). "Among the ligands of LIFR, LIF is overexpressed and has been identified playing a tumor-promoting role in various tumors, including prostate, nasopharyngeal, breast, gastric, endometrial, colorectal, melanoma, osteosarcoma, lung and pancreatic cancers." (PMID 36925915, 2023). "This engineered ‘ligand trap’, fused to an antibody Fc-domain, has ~50-fold increased affinity (~20 pM) and improved LIF inhibition compared to wild-type LIFR-Fc, potently blocks LIF-mediated effects in pancreatic cancer cells, and slows the growth of pancreatic cancer xenograft tumors." (PMID 33846527, 2021). "Since there are robust evidence that the LIF/LIFR pathway exerts a pro-oncogenic role in PDAC cell lines, and because FXR expression is increased in human PDAC tissues, we have focused our attention on the role that natural and synthetic steroids exert in modulating pancreatic cancer cell lines." (PMID 36998446, 2023). "Because these data suggest that the LIF/LIFR pathway is modulated in PDAC tissues, we then investigated whether LIF/LIFR expression undergoes the same regulation in two pancreatic cancer lines, MIA PaCa-2 and PANC-1, which are widely used as in vitro models for PDAC." (PMID 36359879, 2022).
hepatocellular carcinoma (17 papers, 2012 to 2025). A malignant tumor that arises from hepatocytes. "Leukemia inhibitory factor receptor (LIFR) expression is reduced in hepatocellular carcinoma, causing activation of NF-κB signaling through SHP1 and upregulation of the iron-chelating cytokine LCN2." (PMID 38111578, 2023). "Another study on hepatocellular carcinoma investigated the effect of LIFR, leukemia inhibitory factor receptor, in relation to Lcn-2." (PMID 37958332, 2023). "In xenograft tumors derived from hepatocellular carcinoma patients with low LIF receptor subunit alpha expression and high expression of LCN, an LCN2‐neutralizing antibody enhances the ferroptosis‐inducing and anticancer effects." (PMID 36655094, 2023). "The leukemia inhibitory factor receptor LIFR has been shown to act as a suppressor of metastasis in hepatocellular carcinoma." (PMID 27144453, 2016). "In Wurmbach's dataset, we found that level of LIFR mRNA was significantly decreased from liver cell dysplasia to hepatocellular carcinoma with all four probes." (PMID 25749520, 2015). "It was reported that the high expression of LIFR stimulated melanoma cell migration and LIFR negatively regulated the PI-3K/AKT pathway in hepatocellular carcinoma and could function as a metastasis suppressor." (PMID 36062165, 2022). "LIFR suppressed the metastasis of hepatocellular carcinoma via the downregulation of PI3K/AKT31." (PMID 32651426, 2020). "Moreover, LIFR has been reported to inhibit metastasis by negatively regulating the PI3K-Akt-matrix metalloproteinase 13 cascade in hepatocellular carcinoma." (PMID 28629464, 2017). "In hepatocellular carcinoma (HCC), LIFR was found to negatively regulate metastasis via the PI3K/Akt pathway and downregulated expression of LIFR was an indicator of poor prognosis." (PMID 30263091, 2018). "The increase in ERK1/2 activation upon rOSM stimulation of LIF-05-treated hepatoma cells (lane 10) indicated that the OSMR offers higher affinity binding sites for the activation of this MAPK pathway compared to the LIFR." (PMID 22937020, 2012). "In order to characterize the receptor complexes used by rOSM on rat hepatoma cells, we performed RNA interference studies to abrogate the expression of the rat OSMR or blocked the rat LIFR by a LIFR-specific antagonist (LIF-05,)." (PMID 22937020, 2012). "However, LIFR is found to block PI3K/AKT pathway in hepatocellular carcinoma (HCC)." (PMID 30012200, 2018). "The efficiency of LIF-05 in blocking access to the LIFR for other cytokines was proven by the finding that STAT as well as ERK activation in response to both, LIF itself as well as hOSM is strongly impaired upon pretreatment of rat hepatoma cells with LIF-05." (PMID 22937020, 2012). "Therefore, we first defined the signaling capacities of rOSM on rat hepatoma cells since they express gp130, LIFR and OSMR (data not shown)." (PMID 22937020, 2012).
prostate carcinoma (16 papers, 2015 to 2025). A carcinoma that arises from epithelial cells of the prostate gland. "LIFR is highly expressed in melanoma, nasopharyngeal carcinoma, and prostate cancer, and represents poor prognosis." (PMID 40072746, 2025). "The lncAMPC/LIF/LIFR axis has been shown to play a critical role in prostate cancer metastasis and immunosuppression." (PMID 35608100, 2022). "As another example, lncAMPC activates LIF/LIFR/Jak1/STAT3 pathway to stable PD-L1 and metastasis-associated genes, thereby contributing to metastasis and immunosuppression in prostate cancer." (PMID 33665192, 2021). "Our proposal is consistent with a previous study which suggested that LIFr signaling is important in the early stages of prostate cancer progression." (PMID 26329521, 2015). "Additionally, a recent study found that the overexpression of the epidermal growth factor receptor (EGFR) in prostate cancer cells leads to the upregulation of the ligand for the LIF receptor (LIFR)." (PMID 37601653, 2023). "However, a plethora of evidence has indicated that LIFR performs as a marker of poor prognosis and is highly expressed in several types of tumor tissues, such as melanoma and prostate carcinoma." (PMID 36925915, 2023). "As an oncogene, LIFR contributes to the subsequent activation of STAT3 and AKT pathways in prostate cancer, inducing the expression of a series of proliferation-related and transfer genes." (PMID 33505963, 2020).
gastric cancer (12 papers, 2015 to 2025). A primary or metastatic malignant neoplasm involving the stomach. "The LIF/LIFR pathway contributing to gastric cancer is complex with context‐dependent pro‐ versus anti‐tumorigenic roles in GC progression, marking it as a significant biomarker and target for future therapies." (PMID 41163398, 2025). "The LIFR promoter methylation was detected only in the colon cancer cell lines and not in other cancer cell lines such as biliary tract, liver, lung, and stomach cancer cells." (PMID 28751909, 2017). "Down-regulation of LIFR was found in 12 of 20 cancer types, especially cancers of digestive system, such as liver cancer, colorectal cancer, and gastric cancer, through oncomine data-mining analysis." (PMID 25749520, 2015). "Summary of studies investigating LIF/LIFR in gastric cancer." (PMID 41163398, 2025). "Additionally, a study of gastric cancer found that higher levels of LIF and LIFR were associated with increased proliferation, invasion, and metastasis." (PMID 34395259, 2021). "While this study was conducted in PDAC cells, the downstream effects of BAR502—particularly LIFR antagonism and vimentin downregulation—are also relevant in gastric cancer (GC)." (PMID 41163398, 2025). "The potential universality of the miR-221-3p/LIFR pathway is underscored by pan-cancer evidence showing consistent miR-221-3p upregulation and inversely correlated LIFR expression across malignancies, with functional roles established in hepatocellular and gastric carcinomas." (PMID 41272827, 2025). "To functionally characterize the effect of BAR502 as LIFR antagonist, we have then performed in vitro assays using a human macrophage cell line, U937 cells, and liver, HEPG2, PDAC and gastric cancer, MKN45 cell lines." (PMID 36998446, 2023). "Expanding the biomarker landscape to include LIF/LIFR, CLDN18.2, FGFR2b, and other emerging targets is critical to advancing personalized treatment strategies and improving survival outcomes for patients with advanced gastric cancer." (PMID 41163398, 2025). "Interestingly, the role of LIF/LIFR signalling in the gastric cancer context has not yet been thoroughly investigated." (PMID 32707998, 2020). "Indeed, there are only few articles describing LIF/LIFR effects in gastric cancer and none of them addressed CSCs." (PMID 32707998, 2020). "Moreover, the LIFR promoter hypermethylation was found in colon cancer cells only, but not in biliary tract, liver, lung, and stomach cancers cell lines." (PMID 28751909, 2017).
melanoma (12 papers, 2015 to 2025). A malignant, usually aggressive tumor composed of atypical, neoplastic melanocytes. "The leukemia inhibitory factor receptor (LIFR) has been associated with a worse outcome in melanoma patients." (PMID 35267541, 2022). "Higher LIFr expression was also associated with melanoma in males, and AJCC stages III and IV in all patients with melanoma." (PMID 26329521, 2015). "Loss of LIFr expression significantly inhibited melanoma cell migration and inhibited STAT3 phosphorylation." (PMID 26329521, 2015). "In wound healing assays, LIFr knockdown caused 52% reduction in MMRU melanoma cell migration as compared with the control group." (PMID 26329521, 2015). "Maybe the loss of LIFR due to LMNB1 knockdown results in reduction of the stemness like properties of melanoma cells leading to senescence." (PMID 35883595, 2022). "In vitro studies indicated increased expression of LIFR in melanoma cells as compared to melanocytes." (PMID 34068679, 2021). "Conversely, and in relation to its pleiotropic effects, high LIFR expression was found to promote melanoma cell migration and unfavourable prognosis for melanoma patients as well as aggressiveness of chordomas." (PMID 32707998, 2020). "High expression of LIFr identifies very malignant melanocytic lesions at an early stage, and it is a crucial condition for the nevus/implanted melanoma transition." (PMID 30899759, 2019). "Multiple genetic alterations of LIFR have been detected in breast, lung, liver, melanoma, prostate and head-and-neck cancers (data extracted from cBioportal database)." (PMID 30504771, 2018). "Melanomas have been reported to express high level of LIF and LIFR, which are associated with poorer prognosis." (PMID 30504771, 2018). "We found that silencing LIFr significantly suppressed melanoma cell migration, and LIFr knockdown reduced stress fiber formation and melanoma cell motility." (PMID 26329521, 2015). "Primary melanoma patients with strong LIFr expression had worse mean overall, and disease-specific, patient survival compared to patients with low LIFr expression (overall survival, P = 0.0000; disease-specific survival, P = 0.0000, log-rank test)." (PMID 26329521, 2015). "The increased LIFr protein and mRNA expression in melanoma cell lines was consistent with TMA observations." (PMID 26329521, 2015). "Multivariate Cox regression analyses indicated that increased LIFr expression was an independent prognostic marker for primary melanoma (P = 0.036)." (PMID 26329521, 2015). "LIFr knockdown inhibited melanoma cell migration in wound healing assays and reduced stress fiber formation." (PMID 26329521, 2015). "We found that increased LIFr expression correlated with patients aged over 60 years, thick tumors, tumor ulceration, and nodular melanoma in primary melanoma." (PMID 26329521, 2015). "LIFr staining was significantly increased in primary melanoma compared to dysplastic nevi (P = 0.0003) and further increased in metastatic melanoma (P = 0.0000)." (PMID 26329521, 2015). "In this study, we investigated the expression pattern of LIFr in melanoma and assessed its prognostic value." (PMID 26329521, 2015). "Our data showed that most melanoma cell lines expressed higher LIFr protein and mRNA compared to normal melanocytes." (PMID 26329521, 2015). "Studies in vitro suggested that knockdown of LIFr expression inhibited melanoma cell migration through STAT3 (signal transducer and activator of transcription 3) suppression rather than YAP (Yes-associated protein) signaling pathways." (PMID 26329521, 2015). "Instead, eliminating LIFr in melanoma cells markedly reduced STAT3 mRNA expression and inactivated STAT3 by inhibiting its phosphorylation." (PMID 26329521, 2015). "Nodular melanoma, which has metastatic potential, exhibited significantly higher LIFr expression compared with superficial spreading melanoma and lentigo malignant melanoma (P = 0.0000 and 0.0002 respectively)." (PMID 26329521, 2015).
melanoma (continued). "Since LIF signals through formation of heterodimers between a specific LIF receptor (LIFr) and the common IL-6 family co-receptor gp130, a strong rationale exists to investigate the expression and potential role of LIFr in melanoma tumorigenesis." (PMID 26329521, 2015). "We examined LIFr expression in different melanoma cell lines and normal melanocytes by Western blot and reverse transcriptase–quantitative PCR (qPCR)." (PMID 26329521, 2015). "JunBlo microglia reduced melanoma proliferation and migration, while JunBhi microglia preserved the ability of melanoma cells to proliferate in three-dimensional co-cultures, that was abrogated by targeting leukemia inhibitory factor receptor (LIFR) in control microglia–melanoma spheroids." (PMID 37894348, 2023). "The 3D co-cultures of melanoma with JunB-overexpressing microglia protected melanoma cells from the growth-restraining effect mediated by LIFR inhibition, further confirming that LIFR positively regulates MBM cell proliferation predominantly by microglial JunB." (PMID 37894348, 2023). "LIFr knockdown inhibits the migration of melanoma cells in wound-healing tests." (PMID 34295890, 2021). "LIF receptor (LIFR) is also involved in the progression of melanoma." (PMID 34068679, 2021). "LIFr expression is a crucial condition for nevus/implanted melanoma transition; LIFr knockdown inhibits migration of melanoma cells in wound-healing tests; thus, LIFr could be a potential target for developing therapies in initial tumor interventions." (PMID 30899759, 2019). "LIFr knockdown inhibits melanoma cell migration in wound-healing tests." (PMID 30899759, 2019). "Here, we found that LIFr expression was significantly increased in different stages of human melanocytic lesions and LIFr was an independent prognostic factor for survival of melanoma patients." (PMID 26329521, 2015). "From our results, we propose that increased LIFr expression in nevi may serve as an early alarm signal for the transformation from nevus to melanoma." (PMID 26329521, 2015). "However, the specific constitution of the receptor complex and the exact cellular nature of STAT3/LIFr expression in melanoma cells needs further investigation." (PMID 26329521, 2015). "In summary, we found that increased LIFr expression is significantly correlated with melanoma progression and LIFr is an independent factor for predicting disease-specific 5-year survival in primary melanoma patients." (PMID 26329521, 2015). "We hypothesized that the three pathways might be the signaling mechanism(s) by which LIFr impacts melanoma cell migration." (PMID 26329521, 2015). "In all melanoma samples the mean overall 5-year survival in the low LIFr expression group was 75.6% compared to 39.6% in the high LIFr expression group; a significant difference by log-rank analysis (overall survival, P = 0.0000; disease-specific survival, P = 0.0000, log-rank test)." (PMID 26329521, 2015). "LIFr knockdown reduces melanoma cell migration in part by reduced activation of MMP2." (PMID 26329521, 2015). "Based on these findings, LIFr may be used as a prognostic marker of patient survival and blocking LIFr activity may be a potential therapeutic approach for malignant melanoma." (PMID 26329521, 2015). "We sought to investigate the influence of LIFr on these signaling cascades in melanoma cells." (PMID 26329521, 2015). "Increased or decreased expression of LIF receptor (LIFr) has been reported in several human cancers, including skin cancer, but its role in melanoma is unknown." (PMID 26329521, 2015). "Since both MMP2 and LIFr could influence primary melanoma patient survival, and up-regulation of MMP2 plays a crucial role in melanoma cell migration, we investigated the correlation between MMP2 and LIFr expression." (PMID 26329521, 2015).
melanoma (continued). "As LIFr expression progressively increases from primary melanoma to metastatic melanoma, and LIFr activation regulates metastatic behavior, we investigated whether LIFr affects melanoma cell migration and invasion." (PMID 26329521, 2015). "This indicates that LIFr may be important in early melanoma progression; high LIFr expression could identify subgroups of high-risk melanoma patients with reduced chances of survival at an early stage." (PMID 26329521, 2015). "A high LIFr expression is crucial for tumor implantation: analysis of 90 nevi and 441 melanomas shows that LIFr expression is low for all nevus stages, starts to increase in dysplastic nevi, becomes higher in implanted melanomas, and is highest in metastatic melanomas." (PMID 34295890, 2021). "Consequently, we hypothesized that LIFr affects stress fiber formation and subsequently influences melanoma cell migration." (PMID 26329521, 2015). "Therefore knockdown of LIFr may reduce melanoma cell migration via inhibition of STAT3, partly involving p38." (PMID 26329521, 2015). "Melanoma-derived LIF reprogrammed the molecular and functional phenotype of LIFR-expressing microglia cells." (PMID 37894348, 2023). "Considering the similar alterations of LIF/LIFR between NPC and melanoma, systemically analyzing the omics data of these two cancers will provide insightful information regarding to the role of LIF/LIFR in cancers." (PMID 30504771, 2018). "After LIFr knockdown, the active MMP2 consolidated from melanoma cell conditioned medium was reduced, indicating that LIFr helps activate MMP2." (PMID 26329521, 2015). "Our data suggests that LIFr enhances STAT3 production and activation consequently modifying melanoma cell features." (PMID 26329521, 2015). "The percentage of cases with high LIFr expression was also increased in melanoma tissues with ulceration (55.3%) compared to melanoma tissues without ulceration (20.8%) (P = 8.8e-7; χ2 test)." (PMID 26329521, 2015). "Our data using TMA technology showed that there was no strong LIFr expression in normal nevi; LIFr was significantly increased in primary melanoma, and further increased in metastatic melanoma, compared to dysplastic nevi." (PMID 26329521, 2015). "Therefore, we focused on the LIF/LIFR axis and demonstrated (in three out or four MBM cell lines used in this study) that microglial LIFR activation by LIF in melanoma-exposed microglia induces downstream signaling of the JAK/STAT3 pathway, leading to JunB upregulation." (PMID 37894348, 2023). "Moreover, multivariate Cox regression analysis revealed that LIFr expression is an independent factor for predicting disease-specific 5-year survival in primary melanoma, but not metastatic melanoma patients." (PMID 26329521, 2015). "The results indicate that LIFr does not significantly affect the growth rate of melanoma cells." (PMID 26329521, 2015). "LIFr knockdown correlated with STAT3 suppression, but not YAP, suggesting that LIFr activation might stimulate melanoma cell migration through the STAT3 pathway." (PMID 26329521, 2015).